IRF1 (interferon regulatory factor 1)
Diseases named in the same sentence as IRF1 in open-access papers (continued):
Sharing a sentence is not in itself a finding about the gene and the disease.
iron deficiency (1 paper, 2022). "Our results show that Irf1 is specifically required for hyphal formation induced in iron deficiency." (PMID 36004328, 2022). "As expected, IRF1 overexpression was able to rescue C. albicans grown under iron deficiency conditions (BPS, +ATc)." (PMID 36004328, 2022). "The upstream signalling pathways that lead to the activation of Irf1 during iron deficiency stress are still unknown and waiting to be discovered." (PMID 36004328, 2022). "Interestingly, EFG1 and BRG1 are also required for hyphal formation mediated by IRF1 overexpression under normal growth conditions, indicating that the Irf1-mediated hyphal programme corresponds to the hyphal programme induced in iron deficiency." (PMID 36004328, 2022). "The results thus support the hypothesis that Irf1 plays only a minor role in the stress response to iron deficiency, at least with respect to the regulation of iron acquisition." (PMID 36004328, 2022). "While the transcript level of IRF1 itself was increased more than 40-fold by TET-promoter induced overexpression, iron deficiency resulted in a 16-fold increased transcript level, indicating that expression of IRF1 is modulated by iron." (PMID 36004328, 2022). "The overexpression of IRF1 was also able to complement the BPS sensitivity phenotype of a hap5-mutant; HAP5 encodes a subunit of the CCAAT-binding complex, which is essential for growth under iron deficiency conditions." (PMID 36004328, 2022).
kidney (1 paper, 2021). "Similarly, miR-30c-5p agomir which directly inhibits Interferon regulatory factor 1 (IRF1) reduced kidney ischemic injury by reducing M1 macrophages and increasing of M2 macrophages, and by reducing inflammatory cytokine TNF-α and increasing anti-inflammatory cytokines IL-4 and IL-10." (PMID 34421643, 2021).
leiomyosarcoma (1 paper, 2021). An uncommon, aggressive malignant smooth muscle neoplasm, usually occurring in post-menopausal women. "Compared to the non-tumor tissues, the expression levels of both IRF-1 and MFNG were significantly lower in 11 types of sarcoma including leiomyosarcoma, myxoid/round cell liposarcoma, and malignant fibrous histiocytoma." (PMID 34277600, 2021).
leishmaniasis (1 paper, 2022). Infectious disease that is transmitted through the bite of hematophagous female phlebotomine sand flies. "The lack of IRF1 shows a dramatically exacerbated leishmaniasis disease in L. major–infected mice associated with a decrease of IFN-γ and IL-12 productions." (PMID 35992159, 2022).
Listeria infection (1 paper, 2015). "IRF1 could promote CD8+T cell maturity and induce a shift of the Th subset balance to a Th1 dominant state during Listeria infection, as well as activating expression of the cytokine Interferon beta like IRF7." (PMID 26465882, 2015).
liver cirrhosis (1 paper, 2020). "IRF-1 was detectable in hepatocytes of patients with liver cirrhosis, whereas GSK-3 co-localized not only with markers of hepatocytes, but also with markers of liver macrophages." (PMID 33584648, 2020). "To further explore the in vivo relevance of our findings, we assessed IRF-1 and GSK3-expression in liver specimens of patients with liver cirrhosis." (PMID 33584648, 2020).
liver dysfunction (1 paper, 2017). "Moreover, IRF-1 contributed to P38 induced autophagic and apoptotic cell death, that can play a key role in liver dysfunction." (PMID 28266555, 2017).
lymphopenia (1 paper, 2025). Reduction in the number of lymphocytes. "In line with this, we observed elevated expression of pro‐apoptotic molecules (e.g. CASP3, FAS, CASP8, IRF1 etc.)in coinfected patients with severe disease, suggesting that cell apoptosis may be associated with the lymphopenia observed in severe coinfection." (PMID 41163794, 2025).
medulloblastoma (1 paper, 1998). A malignant, invasive embryonal neoplasm arising from the cerebellum. "We analysed a medulloblastoma cell line, ONS-76, as a CNS-derived model system and generated its derivatives, R1 and R2 cells, which constitutively expressed each mouse IRF-1 and IRF-2 cDNA at high levels." (PMID 9649118, 1998).
metabolic syndrome X (1 paper, 2022). "For example, in the subnetwork for metabolic syndrome X, pathogenesis genes AGTR2 and ADRA1A are at the top hierarchical layer for chemokine signaling, while IRF1, MXZB1, MTTP, and CNTC are at the top layer in cytokine signaling." (PMID 35404985, 2022).
metastasis (1 paper, 2020). The spread or migration of cancer cells from one part of the body (where they first appeared) to another. "Correlation analysis results showed that interferon regulatory factor 1 (IRF1) was associated with tumor stage, lymph node metastasis, and distant metastasis." (PMID 32925784, 2020).
microphthalmia (1 paper, 2024). Congenital or developmental anomaly in which the eyeballs are abnormally small. "Further upstream of the caspases in the apoptosis pathway, XAF1 (LFC +5.26, p < 0.0001), IRF1 (LFC +1.53, p < 0.000341), and STAT1 (LFC +1.850, p < 0.000000118) and pro-apoptotic genes BIRC3 (LFC +2.39, p < 0.00000695) and BIK (LFC +1.43, p < 0.00178) was upregulated in microphthalmia patients." (PMID 38821055, 2024).
microscopic polyangiitis (1 paper, 2021). Microscopic polyangiitis (MPA) is an inflammatory, necrotizing, systemic vasculitis that affects predominantly small vessels (i.e. small arteries, arterioles, capillaries, venules) in multiple organs. "MPO/ANCA-positive EGPA has a significant association with HLA class II DQ haplotype, which is shared with the other MPO-AAV (i.e., microscopic polyangiitis, MPA), while ANCA-negativity is associated with GP33 and IL5/IRF1 loci, indicating a possible mucosal/barrier dysfunction origin." (PMID 33718405, 2021).
Mycobacterium avium infection (1 paper, 2021). "We have previously identified the transcription factor IRF1 to be consistently activated in macrophages during Mycobacterium avium infection, but its precise role during infection is not clear." (PMID 34607464, 2021).
myocarditis (1 paper, 2023). Myocarditis is a condition that is characterized by inflammation of the heart muscle (myocardium). "IRF1, a target gene of the IFNγ signaling pathway, was also downregulated at the myocarditis state." (PMID 37264110, 2023).
nasopharyngeal carcinoma (1 paper, 2023). A carcinoma arising from the nasopharyngeal epithelium. "In nasopharyngeal carcinoma cells, super-enhancers are enriched of BRD4, NF-κB, IRF1 and IRF2 transcription factors at the loci of critical oncogenes such as ETV6, high expression of which in human nasopharyngeal carcinoma tissues is correlated with poor patient prognosis." (PMID 38135679, 2023).
neurofibroma (1 paper, 2017). An intraneural or extraneural neoplasm arising from nerve tissues and neural sheaths. "Our gene expression data suggested the possibility that prolonged reduction of IFN-α/β in neurofibroma leads to the expression of IFN-γ and its target genes Csf1, Lif, Irf1, and Casp1 in SCs, possibly contributing to the recruitment and maturation of macrophages." (PMID 28256556, 2017).
Osteopenia (1 paper, 2014). Osteopenia is a term to define bone density that is not normal but also not as low as osteoporosis. "Likewise, it will be interesting to investigate a possible role of IRF1 and of its heterodimerization partner IRF8 in human disorders characterized by osteopenia, such as osteoporosis." (PMID 24954358, 2014).
osteoporosis (1 paper, 2014). A condition of reduced bone mass, with decreased cortical thickness and a decrease in the number and size of the trabeculae of cancellous bone (but normal chemical composition), resulting in increased fracture incidence. "Although genome-wide association studies have identified positive genetic associations with markers in the proximity of the IRF1 (5q31.1) and IRF8 (16q24.1) genes, a role for these genes and their targets in clinical osteoporosis needs to be formally tested." (PMID 24954358, 2014).
papillary thyroid cancer (1 paper, 2023). "For example, the chimeric RET/PTC (rearranged in transformation/papillary thyroid carcinoma) oncoproteins were constitutively expressed in papillary thyroid cancer and were able to phosphorylate the Tyr-107 of STAT1, which is accompanied by IRF1 expression." (PMID 37047709, 2023).
peripheral nerve injury (1 paper, 2019). Injury to a peripheral nerve. "Furthermore, the expression of IL-1β in IRF8-expressing reactive microglia in Peripheral nerve injury is dependent on IRF1 further suggesting the existence of an IRF1/8 regulome." (PMID 31178872, 2019).
Pneumocystis infection (1 paper, 2010). "Both Irf-1 and Irf-8 genes were down-regulated by dexamethasone (-1.52 and -1.61, respectively) but up regulated by Pneumocystis infection (4.45 and 2.13 fold, respectively)." (PMID 20377877, 2010). "Among the genes that were affected by dexamethasone and further affected by Pneumocystis infection, Mgst1 and Hspa1b genes were down-regulated, while Cd14, Irf8, Il1b, Cxcl13, Cxcr4, Fn1, Irf1, Cd74, S100a9, and Spp1 genes were up-regulated in all four groups." (PMID 20377877, 2010).
Pneumocystis pneumonia (1 paper, 2021). "Furthermore, upon analysis, we found a number of TFs either down- or upregulated that have been previously implicated in Pneumocystis AM interactions, including previously upregulated TFs Irf1, and Nfkb1, and in the murine Pneumocystis pneumonia (PCP) model, we observed the downregulation of Egr1." (PMID 34066663, 2021).
psychosis (1 paper, 2021). "Our findings suggest that alterations to activity of the IRF8/IRF1 regulome may underlie the IFN-γ signature changes and drive the monocyte phenotype shifts observed in individuals with psychosis." (PMID 34054608, 2021).
retinal diseases (1 paper, 2022). "Firstly, which retinal diseases in which IRF1 is implicated are needed to be clarified?" (PMID 36498991, 2022). "As an initial step, experimental models of retinal diseases created in the IRF1-KO mice (#002762, Jackson Labs, Bar Harbor, ME, USA) and the WT controls can be adapted to elucidate IRF1’s involvement in pathological processes of retinopathies." (PMID 36498991, 2022).
sarcoma (1 paper, 2021). A usually aggressive malignant neoplasm of the soft tissue or bone. "Afterward, we constructed an immune infiltration-related risk score model based on the expression of IRF1, MFNG, hsa-miR-940, and hsa-miR-378a-5p, presenting a promising performance in predicting the prognosis of patients with sarcoma." (PMID 34277600, 2021).
SARS-CoV infection (1 paper, 2025). "Of these, 16 IRF1-correlated pathways were associated with both ARDS risk and patient survival; notably, three of these pathways were related to SARS-CoV infection or therapy." (PMID 40420582, 2025).
schizophrenia (1 paper, 2023). A major psychotic disorder characterized by abnormalities in the perception or expression of reality. "As a specific peripheral immune biomarker, the expression level of IRF1 is decreased in patients with schizophrenia." (PMID 37383091, 2023).
scleroderma (1 paper, 2023). Scleroderma is a rare autoimmune connective tissue disorder characterized by abnormal hardening of the skin and, sometimes, other organs. "Importantly, MKP-1 supports Th1 polarization by inducing interleukin-12 (IL-12) expression through interferon regulatory factor 1 (IRF1), which could be important in preventing Th2-supported fibrotic processes and development of scleroderma." (PMID 36902103, 2023).
skin cancer (1 paper, 2023). "Of the five MOBILE-hypothesized connector genes (BST2, CLIC2, FAM83D, ACSL5, and HIST2H2AA3) between IRF1 and PD-L1, BST2 was recently recognized as part of an immune/tumor-related signature that is significantly associated with the overall survival of skin cancer patients." (PMID 37414767, 2023).
skin inflammation (1 paper, 2019). "Hh also reduced expression of other genes for inflammatory signaling pathways implicated in skin inflammation including TNFR (Tnfrsf25), JAK-STAT (Jak1), and NF-κB (Trl4, Myd88, Cd69, Cd48, Irf1)." (PMID 31264977, 2019).
skin squamous cell carcinoma (1 paper, 2013). A carcinoma arising from the squamous cells of the epidermis. "However, IRF1 may not always act as a tumor-suppressor, as there is a report that it is upregulated in skin squamous cell carcinoma." (PMID 24564251, 2013).
Splenomegaly (1 paper, 2025). Abnormal increased size of the spleen. "In contrast, B cell-specific IRF-1 deficiency did not result in a further decrease of an already attenuated splenomegaly observed in the N36S MHV68-infected mice." (PMID 41263556, 2025).
steatosis (1 paper, 2025). Increased lipid within the cytoplasm of cells. "Global analysis of the activities of 500 transcription factors using promoter motif inference (see Experimental Section) showed that activities of RELA and IRF1, known mediators of steatosis, liver inflammation, and injury, were significantly increased in MASH." (PMID 39605182, 2025).
toxoplasmosis (1 paper, 2021). A parasitic disease contracted by the ingestion or fetal transmission of toxoplasma gondii. "The relationships between toxoplasmosis, in which STAT1 and IRF1 were highly involved, and ASD have been widely studied." (PMID 34946850, 2021).
type 1 diabetes (1 paper, 2017). "Most remarkably, we identify a common missense variant in IL27, associated with type 1 diabetes that results in decreased functional activity of the protein and reduced expression levels of downstream IRF1 and STAT1 in CD4+ T cells only." (PMID 28248954, 2017).
type 2 diabetes (1 paper, 2024). "Additionally, individuals with both type 2 diabetes (T2D) and PD exhibit increased levels of the pro-inflammatory transcription factors STAT1 and IRF1 along with a decrease in JMJD3 expression in circulating monocytes." (PMID 39315124, 2024).
urothelial carcinoma (1 paper, 2022). A malignant neoplasm derived from the transitional epithelium of the urinary tract (urinary bladder, ureter, urethra, or renal pelvis). "Our previous studies found a co-expression network associated with CD8+ T lymphocyte invasion in urothelial carcinoma, which contains PSMB8, PSMB9, PSMB10, PSME2, IRF1 and other genes." (PMID 36700205, 2022).
vasculitis (1 paper, 2013). "Ifng also enhances expression of Irf1, Irf7, and Irf9, transcription factors that regulate the expression of immune-related genes that may also lead to severe inflammation of the arteries and subsequent lethal vasculitis." (PMID 24063402, 2013).
Venezuelan equine encephalitis (1 paper, 2012). A condition caused by infection by the Venezuelan equine encephalitis virus, which is characterized by headache, fever, myalgia, nausea, and vomiting. "The IRF1 transcription factor was previously found to exhibit antiviral activity against a number of viruses, including the alphaviruses Venezuelan equine encephalitis and chikungunya viruses." (PMID 22615998, 2012).
Yersinia infection (1 paper, 2012). "Recently, expression of IRF-1 was shown to be induced following Y. pseudotuberculosis infection though the role of this transcription factor during Yersinia infection has not been investigated." (PMID 22911267, 2012).
tumor (506 papers, 2003 to 2026). "The discussed observations demonstrate that tumor surveillance by the immune system is compromised by IRF1 loss." (PMID 40110195, 2025). "IRF1, also mutated in 4/7 cases (57%), both suppresses tumor cell growth and stimulates an immune response against tumor cells." (PMID 40670673, 2025). "In cancer research, CARINH has been found to interact with transcriptional co-activators DHX9, ILF3 to regulate the expression of IRF1, with its loss contributing to tumor progression." (PMID 41283334, 2025). "Initially, identified for its role in inflammation, IRF1 has been implicated in promoting tumor growth and progression." (PMID 40025540, 2025). "IRF1 acts as a tumor suppressor and encodes a transcription factor that plays a key role in the body’s defense against infections, cell proliferation, and immune responses." (PMID 40110195, 2025). "The rs2522057, located in an intron of C5orf56, was associated with IRF1 gene expression (a gene with BC tumor suppressor functions) and histone modifications." (PMID 40004528, 2025). "We observed a diverse repertoire of candidate tumor antigens (TAs), IRF1 signaling activity and elevated expression of antigen processing and presentation genes, strongly associated with a “hot” tumor immune microenvironment (TIME)." (PMID 40894019, 2025). "Several studies have shown that IRF1 is associated with tumor suppression, the development of natural killer (NK) cells and T-cells, and B-cell biology." (PMID 39874788, 2025). "IRF1 has been shown to upregulate CD274 (that encodes PD-L1) expression in the tumor microenvironment and IRF1 “knock-out” has been shown to render tumor cells more susceptible to CD8+ T cell-mediated killing." (PMID 40428397, 2025). "Increased levels of IRF1 in tumor cells in this study were associated with increased secretion of IFNγ by infiltrating NK and NKT cells and with induction of apoptosis by the CXCL10/CXCR3 paracrine axis." (PMID 38396830, 2024). "In circulating tumor cells, PD-L1 and IRF1 expression levels are all associated with immunotherapy efficacy." (PMID 38915471, 2024). "CD44 showed an increase in exon usage to result in tumour associated forms and IRF1 with loss of DNA binding region." (PMID 37091785, 2023). "Here we report a case of BPDCN with a novel AFF4::IRF1 fusion predicted to lead to a loss-of-function of the IRF1 tumor suppressor, somatic mutations of ASXL1, TET2, and MYD88, as well as multiple intrachromosomal deletions." (PMID 38203475, 2023). "IRF1 loss combined with other genetic alterations prominently increases tumor incidence of many organs in mice." (PMID 37090158, 2023). "A trend of increasing TLR9 and IRF1 mRNA expression, associated with a pro-inflammatory, anti-tumor phenotype was observed in BMDMs treated with both RXR agonists." (PMID 36901727, 2023). "Genetic deficiencies in the IFNγ pathway in the tumor cells hinders activation of the regulatory factor IRF1 and subsequent transcription of the PD-L1 gene." (PMID 37620318, 2023). "IRF1 encodes a protein that serves as an activator for genes involved in immune responses and it plays a key role in tumor suppression." (PMID 37175757, 2023). "Tumor cells primed with interferon regulatory factor 1 (IRF-1), a transcription factor associated with antitumor immunity, secrete EVs containing high levels of IRF-1 target genes, MHC I, and IL-15Rα." (PMID 38138963, 2023). "The tumor suppressor nature of IRF1 has been linked to its pro-apoptotic property, and it acts as an effector of IFNs that suppress proliferation in many cancers." (PMID 37094077, 2023). "Originally discovered and best-studied in the context of the antiviral innate immune response, IRF1 has been implicated in the DNA damage response and tumor suppressor functions." (PMID 35436994, 2022).